ADAM10 (ADAM metallopeptidase domain 10)
Diseases named in the same sentence as ADAM10 in open-access papers (continued):
Sharing a sentence is not in itself a finding about the gene and the disease.
adenoid cystic carcinoma (1 paper, 2010). A malignant tumor arising from the epithelial cells. "Importantly, in the present study, we discovered a significant growth inhibition of adenoid cystic carcinoma cells following downregulation of ADAM10 via ADAM 10-specific siRNA, which suggested that ADAM 10 is a promising new therapeutic target for the treatment of adenoid cystic carcinoma." (PMID 21171968, 2010).
allergic rhinitis (1 paper, 2025). Inflammation of the nasal mucous membranes caused by an IgE-mediated response to external allergens. "There was other evidence that ADAM10 and ADAM17 influenced allergic rhinitis, which are also transmembrane metalloproteases." (PMID 40761581, 2025).
Alzheimer disease 18 (1 paper, 2023). Any Alzheimer disease in which the cause of the disease is a mutation in the ADAM10 gene. "ADAM10 is associated with Alzheimer’s disease 18 (OMIM 615590), and reticulate acropigmentation of Kitamura (OMIM 615537)." (PMID 37240249, 2023).
ameloblastoma (1 paper, 2022). The most common odontogenic tumor, arising from the epithelial component of the embryonic tooth and usually affecting the molar-ramus region of the mandible or maxilla. "With these bioinformatic analyses it is possible that pathogenic ameloblastoma development involve these genes in intracellular regulation (AKT1, ACTC1, ADAM10, and APOA2) or for tumor microenvironment regulation (CRP, BCHE, APP, AGT)." (PMID 36553196, 2022).
amelogenesis imperfecta (1 paper, 2022). Amelogenesis imperfecta (AI) represents a group of developmental conditions affecting the structure and clinical appearance of the enamel of all or nearly all the teeth in a more or less equal manner, and which may be associated with morphologic or biochemical changes elsewhere in the body. "Currently, no mutations in ADAM10 have been reported in amelogenesis imperfecta in humans and mice; therefore, the role of ADAM10 in amelogenesis imperfecta is unclear." (PMID 35401675, 2022).
anaphylaxis (1 paper, 2018). An acute hypersensitivity reaction that occurs from exposure to an allergen. "Moreover, ADAM10 and its ligand Notch1 were shown to be essential for DCs to produce Th2 type cytokines in a murine model of IgE-mediated anaphylaxis, suggesting that ADAM10 activation by Hla could have pro-allergenic effects." (PMID 30111706, 2018).
arthropathy (1 paper, 2021). Any disorder of the joints. "ADAM10 expression in healthy cartilage tissue is low, but increases in joint diseases, stimulated by pro-inflammatory cytokines." (PMID 33668781, 2021).
astrocytoma (1 paper, 2021). "This interaction could be verified both by co-localization seen with immunofluorescence of the endogenous proteins in human astrocytoma cells (U-373MG) and by co-immunoprecipitation followed by western blotting from lysates of COS-7 cells co-transfected with (cDNA)ADAM10 and (cDNA) APCN." (PMID 34481452, 2021).
autosomal dominant polycystic kidney disease (1 paper, 2018). Autosomal dominant form of polycystic kidney disease. "The effects of ADAM10 activation on E-cadherin shedding was actually reported in ADPKD (autosomal dominant polycystic kidney disease)." (PMID 30460232, 2018).
B cell lymphoma (1 paper, 2021). "It has been further reported that TNFα-induced apoptosis can be regulated via an ADAM10-NF-κB feedback loop in a B cell lymphoma cell line." (PMID 33791311, 2021).
bacterial sepsis (1 paper, 2023). "The ADAM10 rs653765 promoter polymorphism appears to regulate protein expression, suggesting a mechanism by which the SNP may influence the outcome of human bacterial sepsis." (PMID 37788087, 2023).
bladder tumor (1 paper, 2021). "Moreover, we found that the absence of PD-L1 was associated with strong expression of ADAM17 and, although less pronounced, with expression of ADAM10 within both bladder tumor regions." (PMID 33672843, 2021).
brain injury (1 paper, 2021). Acute and chronic (see also brain INJURIES, CHRONIC) injuries to the brain, including the cerebral hemispheres, CEREBELLUM, and brain STEM. "Here, we examined the effects of the ADAM10 inhibitor GI254023X on the neurological and histopathological outcome after experimental traumatic brain injury (TBI)." (PMID 33791311, 2021).
brain ischemia (1 paper, 2020). Diminished or absent blood supply to the brain caused by obstruction (thrombosis or embolism) of an artery resulting in neurologic damage. "In the CA3 region of the hippocampus, the expression of the α-secretase (ADAM10) gene after 10-min brain ischemia with a survival of 2, 7, and 30 days was below the control values." (PMID 31713815, 2020).
cholangiocarcinoma (1 paper, 2025). A carcinoma that arises from the intrahepatic biliary tree (intrahepatic cholangiocarcinoma) or from the junction, or adjacent to the junction, of the right and left hepatic ducts (hilar cholangiocarcinoma). "sMICA in the peripheral blood of cholangiocarcinoma patients is elevated and consistent with the high expression levels of ADAM10 and ADAM17." (PMID 40563539, 2025).
choroidal neovascularization (1 paper, 2022). An eye disorder described by the growth of new blood vessels that originate from the choroid through a break in the Bruch membrane into the sub–retinal pigment epithelium (sub-RPE) or subretinal space. "We further observed around 30% reduction in ADAM10 activity in the choroid/RPE compartment of the mouse eye subjected to laser-induced choroidal neovascularization (CNV)." (PMID 36185601, 2022).
ciliopathy (1 paper, 2022). A genetic disorder of the cellular cilia or the cilia anchoring structures, the basal bodies, or of ciliary function. "If ADAM10 and Lsamp can be confirmed as major players in ciliopathy-associated behavioral phenotypes in future studies, this might be a suitable way to ameliorate behavioral deficits in BBS model mice and patients." (PMID 36498834, 2022).
coagulopathies (1 paper, 2026). "In addition to this, ADAM10’s role in coagulopathies has also been shown recently, as α-toxin stimulation was shown to induce platelet aggregation, while ADAM10 deletion limited both platelet aggregation and the resulting microvascular occlusion." (PMID 41408425, 2026).
conduct disorder (1 paper, 2022). A disorder diagnosed in childhood or adolescence age group characterized by aggressive behavior, deceitfulness, destruction of property or violation of rules that is persistent and repetitive, and within a one year period. "A family-based association study found 20 variants associated significantly associated with conduct disorder; among these single nucleotide polymorphisms (SNPs), rs383902 was located within ADAM10 (p = 0.00036)." (PMID 35444632, 2022). "However, ADAM10/17 have also been linked to SCZ, depression, BPD, and conduct disorder, a condition that has been found to be comorbid with mood disorders." (PMID 35444632, 2022).
corneal disease (1 paper, 2025). "The ADAM10 inhibitor GI254023X blocked neutrophil IL-1β secretion induced by Hla-expressing CC8, but not by CC5 conditioned media, indicating that these Hla polymorphisms play an important role in Hla receptor binding and neutrophil IL-1β secretion, and affect corneal disease severity." (PMID 41415470, 2025).
cortical dysplasia (1 paper, 2019). "Compared with amyloidogenic processes in elderly individuals, ADAM10‐mediated cortical dysplasia is distinct and is most likely caused by a non‐amyloidogenic pathogenic mechanism in early‐onset epilepsy." (PMID 31087543, 2019). "In addition, ADAM10 functions in brain development, and the loss of function of this molecule can result in cortical dysplasia, followed by refractory seizures, indicating that ADAM10 is also involved in late‐onset epilepsy." (PMID 31087543, 2019). "Interestingly, this seeming contradiction conforms to the stage‐dependent involvement of ADAM10 in amyloidogenic processes and cortical dysplasia." (PMID 31087543, 2019). "As ADAM10 is a key modulator of cortical dysplasia, screening for ADAM10 genetic variations might contribute to early recognition of high‐risk individuals with cortical dysplasia‐related epilepsy." (PMID 31087543, 2019). "Several potential targets for seizure control, such as candidate transcription factors and microRNAs that regulate ADAM10, as well as potential genetic screening tools for the early recognition of cortical dysplasia, have been suggested but must be studied in more detail." (PMID 31087543, 2019).
cutaneous melanoma (1 paper, 2015). A primary melanoma arising from atypical melanocytes in the skin. "The aim of the study was to assess the expression and intracellular location of ADAM-10 in 104 primary skin melanomas and 16 metastatic lesions from regional lymph nodes." (PMID 26266086, 2015). "Other parameters of ADAM-10 expression in primary tumor and nodal metastasis cells did not have a statistically significant impact on the prognosis in cutaneous melanoma patients in the analyzed group of patients." (PMID 26266086, 2015). "Review of the literature shows that our study is the first one ever to describe the significance of ADAM-10 expression in correlation with detailed histopathological parameters of the primary tumor and data on long-term survival of cutaneous melanoma patients." (PMID 26266086, 2015).
deep vein thrombosis (1 paper, 2017). "However, the Incyte inhibitor, INCB7839, that targets ADAM10 and ADAM17 and thus almost all shedding events, was in phase II clinical trials where deep vein thrombosis was the only reported side effect." (PMID 29230082, 2017).
delirium (1 paper, 2024). A disorder characterized by confusion; inattentiveness; disorientation; illusions; hallucinations; agitation; and in some instances autonomic nervous system overactivity. "From the LASSO coefficients, the vascular wall biology targets (i.e., F2, ADAM10, and CTSB) all show positive effects, meaning that patients with higher values of these biomarkers are more likely to have delirium." (PMID 38346717, 2024).
E. coli infection (1 paper, 2020). "E. coli infection resulted in the upregulation of the genes encoding proteases, which participate in the degradation of ECM, namely, ADAM10 (logFC of 2.62), ADAM17 (logFC of 8.75), MMP9 and MMP14 (both with a logFC of 2.58), CAPN7 and CAST (both with logFC of 2.20)." (PMID 32234079, 2020).
endotoxemia (1 paper, 2019). "The results showed that treatment with or genetic inhibition of EGR1 triggered significant effects on cytokine and adhesion molecule expression, which further validated the functional pathway of EGR1/ADAM10 in the context of endotoxemia." (PMID 31387910, 2019). "ADAM10 acts as an EGR1 target gene in the mouse endotoxemia model." (PMID 31387910, 2019). "Collectively, these data provide insights into the mechanisms showing that targeting the EGR1/ADAM10 pathway may be a potential therapeutic regimen for mice with endotoxemia driven by LPS." (PMID 31387910, 2019).
focal segmental glomerulosclerosis (1 paper, 2018). A renal disorder characterized by sclerotic lesions in the glomeruli. "ADAM10 expression was assessed in paraffin-embedded renal tissues from 2 patients with chronic interstitial nephritis, 3 with focal segmental glomerulosclerosis, and 1 living donor renal biopsy." (PMID 30117015, 2018). "Moreover, we revealed that ADAM10 expression was increased in the renal tubulointerstitial parts of patients with chronic interstitial nephritis and focal segmental glomerulosclerosis." (PMID 30117015, 2018).
gastric tumors (1 paper, 2018). "In contrast, PGE2 exerts positive effects on the regulation of ADAM-10 expression in mouse gastric tumors, but to the best of our knowledge, the effects of PGE2 on ADAM-10 expression have not been documented in neuronal systems." (PMID 30383537, 2018).
hydronephrosis (1 paper, 2021). Collection of urine in the renal pelvis that results in dilatation of the renal pelvis and calyces. "Though a decreased number of PCs was previously observed in Adam10 KO mice, leading to polyuria and hydronephrosis and suggesting a role for Aqp2 in mediating the KO phenotype, very different mechanisms affecting cell plasticity may be at play." (PMID 34131651, 2021).
Idiopathic Inflammatory Myopathies (1 paper, 2023). "Nevertheless, since proteolytic breakdown is critical for immune cell infiltration thus ensuing tissue destruction in muscle inflammatory disorders, new investigations aimed at understanding the role of ADAM10 in idiopathic inflammatory myopathies are needed." (PMID 36768791, 2023).
inflammatory bowel disease (1 paper, 2013). A spectrum of small and large bowel inflammatory diseases of unknown etiology. "The reduced ADAM10 activity found in meprin β knockout mice would clearly have impact on inflammatory processes such as inflammatory bowel disease, since it has been shown that ADAM10 cleaves inflammatory cytokines." (PMID 22940918, 2013).
intestinal cancer (1 paper, 2020). "Genetic deficiency of ADAM10 in intestinal stem cells drastically reduced colonic and small intestinal adenoma formation in mice with biallelic loss of APC which was linked to the absence of Notch signalling, indicating that ADAM10 is a potential attractive target for intestinal cancer therapy." (PMID 32698506, 2020).
Iron deficiency (1 paper, 2025). "Iron deficiency has been previously reported to activate Furin, a proconvertase that reaches out to the macrophage membrane and cleaves the prodomain of ADAM10 to activate it." (PMID 39888953, 2025).
ischemia (1 paper, 2019). A hypoperfusion of the BLOOD through an organ or tissue caused by a PATHOLOGIC CONSTRICTION or obstruction of its BLOOD VESSELS, or an absence of BLOOD CIRCULATION. "Elevated CSF sPDGFRβ likely reflects release of a soluble fragment of pericyte PDGFRβ, due to its cleavage by ADAM-10, as was shown in vitro in response to simulated ischemia or Aβ peptide." (PMID 31521199, 2019).
ischemic heart disease (1 paper, 2022). "Thus, targeted inhibition of the ADAM10/CX3CL1 axis could interfere with the dynamic events triggering detrimental trained immunity and chronic inflammation in ischemic heart disease." (PMID 36496449, 2022).
islet cell tumor (1 paper, 2015). "Towards this, we analyzed ADAM10 levels by immunohistochemistry in human PDAC tissue microarrays that contained duplicate samples representing normal pancreas, islet cell tumor, and Stage I, II and III adenocarcinomas with regional or distant metastasis." (PMID 26440150, 2015).
keloid (1 paper, 2021). An irregularly shaped, elevated mark on the skin caused by deposits of excessive amounts of collagen during wound healing. "The elevated protease levels in keloid fibroblasts coincided with close proximity to CD45+ immune cells, as ADAM10, ADAM17 and CD10 reveal a high expression predominantly found in lesional fibroblasts." (PMID 34502327, 2021). "While monocyte-derived inflammatory dendritic cells (DC) were the main infiltrating immune cell population, the striking upregulation of ADAM10, ADAM17 and Neprilysine in lesional fibroblasts may point to a prominent role of these proteases in the pathogenesis of keloids." (PMID 34502327, 2021).
kidney cancer (1 paper, 2014). Primary or metastatic malignant neoplasm involving the kidney. "In summary, we report, in kidney cancer, that MUC1 is involved in cancer progression and sheddases ADAM10, ADAM17 and gamma-secretase are necessary for MUC1-C nuclear location and in increase of invasiveness." (PMID 24504508, 2014).
liver failure (1 paper, 2021). A liver disease characterized by the liver losing or has lost all of its function. "Furthermore, aberrant ADAM10 activity in TIMP-3 deficient mice promoted liver failure in a model of hepatic ischemia/reperfusion injury." (PMID 33673623, 2021).
low grade glioma (1 paper, 2025). A grade I or grade II glioma arising from the central nervous system. "Analysis of TCGA data showed elevated expression of ADAM10 in both GBM and low-grade glioma (LGG), relative to normal tissue, correlating with poor prognosis in LGG and also suggesting a role in early disease." (PMID 41226720, 2025).
meningococcal infection (1 paper, 2018). Infections with bacteria of the species neisseria meningitidis. "Therefore, we investigated the role of ADAM10 during meningococcal infection." (PMID 29630665, 2018).
myocardial ischemia (1 paper, 2020). A disorder of cardiac function caused by insufficient blood flow to the muscle tissue of the heart. "Studies have shown that ADAM0 can hydrolyze the receptors of the outer membrane of Notch protein, suggesting that in myocardial ischemia, ADAM10 may induce angiogenesis, inhibit cardiomyocyte apoptosis by activating the Notch signaling pathway, and play a role in improving myocardial ischemia." (PMID 32908925, 2020).
ovarian failure (1 paper, 2025). "In the HIPP, protein content was not significantly different between groups when looking at total APP, sAPPα, sAPPβ, BACE1, the sAPPα/sAPPβ ratio, nor was BACE1 and ADAM10 enzyme activity affected by ovarian failure (P > 0.05)." (PMID 39711362, 2025).
pancreatic ductal adenocarcinoma (1 paper, 2013). An infiltrating adenocarcinoma that arises from the epithelial cells of the pancreas. "While without stimulation ADAM10 was found at comparably high levels on all cell types analyzed, ADAM17 was almost not detectable on T cells and only present at low levels on some tumor cell types, e.g. pancreatic ductal adenocarcinoma (Panc89) and fibrosarcoma (HT1080) cell lines." (PMID 24130797, 2013).
papillary renal cell carcinoma (1 paper, 2023). A rare subtype of renal cell carcinoma, arising from the renal tubular epithelium and showing a papillary growth pattern, which typically manifests with hematuria, flank pain, palpable abdominal mass or nonspecific symptoms, such as fatigue, weight loss or fever. "PRC1 has revealed upper expression in other cancer tissues such as, among others, invasive cervical carcinomas, papillary renal cell carcinoma, pediatric adrenocortical tumour, while yet not being studied in depth as compared to CCNB1, ADAM10 or RACGAP1." (PMID 37438763, 2023).
pemphigus vulgaris (1 paper, 2021). Pemphigus is a group of chronic autoimmune skin diseases characterized by blister formations on the outer layer of the skin and the mucous membranes. "The results demonstrated that ADAM10 and MMP-9 activity is necessary for blister formation in experimental models of pemphigus vulgaris (PV) and BP, respectively." (PMID 34680139, 2021).
periodontitis (1 paper, 2026). An acute or chronic inflammatory process that affects the tissues that surround and support the teeth. "Another way in which IL‐23R isoforms can be formed is by transmembrane cleavage by a disintegrin and metalloprotease 10 and 17 (ADAM10 and ADAM17), of which ADAM17 has been found to be elevated in patients with periodontitis." (PMID 41536464, 2026).
Pleural effusion (1 paper, 2022). The presence of an excessive amount of fluid in the pleural cavity. "Tetraspanin CD9, metalloprotease ADAM10, heat-shock protein HSP70, and annexin-1, in particular, are common marker proteins detected in sera and pleural effusion-derived sEVs from bodily fluids of BC patients and culture supernatants of BC cell lines." (PMID 36499561, 2022).
renal cell carcinoma (1 paper, 2018). "In contrast, down-regulation of ADAM10 produces a flaccid morphological appearance, up-regulation of Slug and E-cadherin loss, as observed during EMT in the renal cell carcinoma cells." (PMID 30117015, 2018).
renal failure (1 paper, 2023). "The role of ADAM10 is demonstrated in the progression of various renal diseases, including acute kidney injury, indicating it is an excellent therapeutic target for many kidney disorders." (PMID 37513824, 2023). "We aimed in our work to find out the possible relation between PAR-2, fibrinogen and ADAM10 in Cis-induced ARF and the possible protective effect of the anticoagulant, fund, or the possible treatment of the fibrinolytic agent, Alt, in Cis-induced renal failure." (PMID 37513824, 2023).